MAT2A (methionine adenosyltransferase 2A)
Diseases named in the same sentence as MAT2A in open-access papers (continued):
Sharing a sentence is not in itself a finding about the gene and the disease.
cancer (continued). "In summary, our results reveal that downregulated expression level of MAT2A is common in cancer tissues of RCC patients." (PMID 24636201, 2014). "In hepatocelluar carcinoma cell, one methionine adenosyltransferase (MAT) isozyme, MATII was found to have two catalytic subunits which were encoded by MAT2A and MAT2β respectively." (PMID 19025580, 2008). "MAT2A's potential as a therapeutic target in cancer treatments has gained attention." (PMID 40191097, 2025). "Surprisingly, MAT2A inhibition exhibits a gratifying result in the MTAP-deleted cancers." (PMID 41445748, 2025). "The inhibition of methionine adenosyltransferase 2A (MAT2A) in cancers harboring deletions of the methylthioadenosine phosphorylase (MTAP) gene induces synthetic lethality, making it a highly compelling strategy in the pursuit of precision anticancer therapeutics." (PMID 40430308, 2025). "Notably, MAT2A is essential for the survival of cancers harboring deletions of the methylthioadenosine phosphorylase (MTAP) gene, which occurs in approximately 13–15% of tumors due to its co-deletion with the CDKN2A tumor suppressor." (PMID 40430308, 2025). "The MAT2A inhibitor, such as IDE397, selectively induces synthetic lethality in MTAP-deficient malignancies, while SLC7A5 inhibitors, such as JPH203, exert anti-cancer activity by blocking SLC7A5." (PMID 40430461, 2025). "Understanding the adaption of processes to the increased MTA concentration in cancer cells with MTAP deletion may be crucial for understanding the causes of resistance to PRMT5 and MAT2A inhibitor therapies." (PMID 41465382, 2025). "Unfortunately, although MAT2A is indeed an excellent potential target for cancer therapy and multiple MAT2A inhibitors are identified in recent years, there still lacks the mature MAT2A inhibitor drug for the clinical application of the broad-spectrum cancers due to various shortages." (PMID 41445748, 2025). "However, the regulatory mechanisms governing MAT2A in the context of cancer cell RNA m6A hypermethylation remain poorly understood." (PMID 40295500, 2025). "Recent studies have found that regulating the activity of MAT2A may provide a new strategy for the treatment of MTAP deletion cancer." (PMID 40240755, 2025). "Some preclinical evidence suggests legitimacy for combining therapy with PRMT5 and MAT2A inhibitors which may produce more robust responses in cancer patients." (PMID 41465382, 2025). "MAT2A inhibitors, such as SCR-7952, show strong and selective anti-tumor activity in both in vitro and in vivo models of MTAP-deficient cancer, and can produce synergistic antitumor effects when used competitively or cooperatively with S-AdenosylMethionine and PRMT 5 inhibitors." (PMID 40240755, 2025). "Diverse studies have shown upregulation of UBC9, BCL2, and MAT2A expression in cancer cells." (PMID 40141131, 2025). "Researchers believe that the vulnerability of PRMT5 in MTAP‐deficient cancers may extend both upstream of PRMT5 (methionine adenosyltransferase 2A, MAT2A) and downstream of PRMT5 (RIOK1 and other PRMT5 co‐complex members)." (PMID 39711357, 2024). "Consequently, in MTAP−/− tumors the synthetic lethal inhibition of MAT2a ultimately converges on PRMT5 inhibition that reduces cancer growth and induces cell death." (PMID 38000655, 2024). "Here, we discuss the rationale and methods for targeting the MAT2A/PRMT5 axis for cancer therapy." (PMID 37795443, 2023). "Both silencing MAT2A and SLC7A6 could decreased the cell proliferation rate of BCa cells, while MAT2A silencing significantly contributes to the cisplatin sensitivity than SLC7A6 in cisplatin resistant cancer cells." (PMID 37582769, 2023).
cancer (continued). "Through multi-omics analysis of metabolomics and proteomics of T24 and T24CR cells, we found that MAT2A regulated methionine metabolism is crucial to cisplatin resistance and cancer stem cell properties in BCa cells, mainly though the regulation of production of SAM for methylated histone turnover." (PMID 37582769, 2023). "Consistently, high expression of MAT2A indicates poor prognosis in different human cancers." (PMID 35729157, 2022). "MAT2A plays a crucial role in various cancer progression, including PCa." (PMID 36497496, 2022). "Importantly, MAT2A inhibitors have anti-proliferative activity in MTAP-deleted cancer cells and tumors, a result that prompted the development of a phase I clinical trial using MAT2A inhibitors (ClinicalTrials.gov NCT03435250)." (PMID 35631199, 2022). "However, mutation of MAT2A MARylation site blocks the regulatory role of SIRT4 and promotes cancer development." (PMID 36371321, 2022). "Finally, the mechanism of action of MTDIA was investigated by assessing PRMT5 activity in treated mice and by generation of an MTAP inhibitor-resistant cell line of FaDu cancer cells, revealing amplification of MAT2A, a known target in MTAP−/− cancers." (PMID 33893330, 2021). "Further investigationis needed to properly understand the cellular regulation of Mat2A,the cellular role of Mat2B, and the potential ramifications that thesefactors may have on cancer therapies." (PMID 34780697, 2021). "The physiologic impact of MTDIA on tissue metabolite levels and arginine methylation were also determined, since elevated MTA can potentially interact with other targets including type 1 PRMTs, PRMT5 and MAT2A by mimicking the metabolic physiology observed in MTAP−/− cancer cell lines." (PMID 33893330, 2021). "It was reported that the deletion of MAT2A will result in proliferation inhibition in cancer cells." (PMID 34063807, 2021). "MTDIA therapy could therefore specifically enhance the sensitivity of cancer cells to PRMT5 or MAT2A inhibitors." (PMID 33893330, 2021). "However, cancer cells can adapt to PF-9366 MAT2A inhibition by upregulating MAT2A, thereby impairing the anti-proliferative effect." (PMID 32824193, 2020). "Recently, increasing studies showed that MAT2A play important roles in cancer progression." (PMID 33138667, 2020). "The gene MATIA was downregulated, and MAT2A was upregulated in one cancer." (PMID 31828117, 2019). "The regulatory role of NF-κB in MAT2A expression was reported in several cancer types." (PMID 26418898, 2016). "Exposure to AFB1 (AFB and PBAFB groups) initiated expression of cancer-associated transcripts (such as MAT2A) not observed in the CNTL or PB groups." (PMID 24979717, 2014). "Therefore, we first examined the transcription level of the MAT2A in cancer tissues and adjacent normal tissues from 24 RCC patients using qRT-PCR." (PMID 24636201, 2014). "This study demonstrated that MAT2A was lower expression in cancer tissues, suggesting that it may be involved in the development of RCC." (PMID 24636201, 2014). "Perhaps PRMT5 and MAT2A inhibitors combined with other treatment methods (immunotherapy, chemotherapy, and molecularly targeted therapies) could be considered as first-line therapy for patients with selected cancers." (PMID 41465382, 2025). "Consequently, MAT2A inhibitors, such as AG‐270, have been developed for cancer therapy." (PMID 40552664, 2025). "Therefore, the local cancer MTAP−/− genotype may be suboptimal for clinical efficacy of MAT2a inhibitors." (PMID 38000655, 2024). "Therefore, targeting MAT2A as a possible strategy for treating cancers (especially in MTAP-negative cancers) may reduce tumour growth." (PMID 37795443, 2023).
cancer (continued). "In addition to the potential epigenetic regulation of histone, MAT2A may affect cancer progression via its interactions with other nuclear proteins." (PMID 34065390, 2021). "The underlying mechanisms for MAT2A/MAT2B parallel induction in these cancers are not clear." (PMID 29108270, 2017). "Given this synthetic lethal interaction, MAT2A has emerged as a promising therapeutic target, with several inhibitors currently in clinical development for the treatment of MTAP-deleted cancers." (PMID 40430308, 2025). "Extensive research has been conducted on the role of METTL16 in regulating cancer progression through m6A modification of target genes, including U6 snRNA, MALAT1, XIST, and RAB11B‐AS1, and mRNA (MAT2A, VPS33B, FGFR4, and GPX4)." (PMID 40095756, 2025). "Besides MAT2A, hypomethylation of U6 snRNA at A43 could result in mis-splicing events that contribute to cancer, for there is a longstanding link between aberrant splicing and cancer." (PMID 41007290, 2025). "MAT2A inhibitors were developed later than PRMT5 inhibitors and only two molecules are in Phase II clinical trials concerning cancer patients with MTAP deletion." (PMID 41465382, 2025). "Prior studies have demonstrated that using MAT2A inhibitors alone can induce MR, reduce SAM levels, and impede the progression of various cancers, including breast cancer, lung cancer, and multiple myeloma." (PMID 40430461, 2025). "We demonstrate that both MAT2a and AHCY are required for proper mitochondrial function in GBM and are necessary to protect cancer cells against oxidative damage." (PMID 40015640, 2025). "Other novel MAT2A inhibitors, such as AGI-41998, exhibit potent inhibitory activity and favorable brain permeability, significantly suppressing cancer growth in xenograft models." (PMID 40430461, 2025). "The high expression of MAT2A and PRMT5 in cancer cells with a homozygous deletion of the MTAP gene appears to be a negative predictive factor of treatment with PRMT5 and MAT2A inhibitors." (PMID 41465382, 2025). "We discovered a potent and specific allosteric MAT2A inhibitor SCR‐7952, with promising inhibition on the growth of MTAP‐deleted cancers, via the regulation of PRMT5 activity and its downstream." (PMID 39309689, 2024). "Supplementation with excess folate can inhibit the degradation of MAT2A through the ubiquitin protein transferase VCIP135, indirectly accelerating the methionine cycle in cancer tissues, and promoting the progression of HCC." (PMID 38931227, 2024). "Our findings underscore the innovative approach of combining VEN with the RNA-directed anti-cancer compounds 8CA/8AA (VEN + 8CA; VEN + 8AA) for AML treatment by targeting the methionine-MAT2A-SAM axis." (PMID 38643304, 2024). "It was reported that IDE397 exhibited inhibition of MAT2A activity with IC50 of about 10 nM and antiproliferation effect on MTAP−/− cancer cells with IC50 of about 20 nM." (PMID 39309689, 2024). "Here, we described a novel MAT2A inhibitor, SCR‐7952 with potent and selective antitumor effects on MTAP‐deleted cancers in both in vitro and in vivo." (PMID 39309689, 2024). "Among them, MAT2A is responsible for SAM synthesis in extrahepatic normal tissue and cancer tissue, MAT1A is only responsible for SAM synthesis in normal liver tissue and bile duct epithelial cells, and MAT2B has no catalytic activity." (PMID 38931227, 2024). "Targeting SAM or MAT2A has proven beneficial among several type of cancers, especially in MTAP-deleted cancers." (PMID 36891236, 2023). "Despite further investigation into possible side effects of limiting methionine intake and/or targeting MAT2A is merited, there is strong evidence showing dietary methionine restriction may not only produce lifespan extension but also prevent several chronic diseases and cancer." (PMID 39872059, 2023). "Tumors that have MTAP and p16 co-deletion are sensitive to inhibition of MAT2A and that makes MAT2A an attractive lethal target for MTAP-deleted cancers." (PMID 36572880, 2022).
cancer (continued). "Studies have shown that a variety of miRNAs, including miR-101-5p, miR-136, miR-942-5p, and miR-485-5p, can target the MAT2A mRNA 3’-UTR, thus regulating cancer progression." (PMID 36555116, 2022). "The combination of methionine depletion and MAT2A inhibition has been used to suppress SAM biosynthesis and eradicate CD44hi/C24low cancer stem cell population." (PMID 34065390, 2021). "Although MTAP deletion frequency is more rare in CRC than in other cancers, some CRC cell lines have been shown to have significantly increased MTAP and MAT2A expression, indicating increased reliance on these metabolic pathways." (PMID 33893330, 2021). "In MTAP deleted cancers, PRMT5 and methionine adenosyltransferase II α (MAT2A) enzymes were identified as synthetic lethal targets." (PMID 34573422, 2021). "The downstream inhibition of PRMT5 is similar to the effects of a MAT2A inhibitor in an MTAP−/− cell line, in that both inhibit cancer cell growth via restriction of PRMT5 activity." (PMID 33893330, 2021). "S-adenosylmethionine (SAM) is the universal methyl donor in human cells and is synthesized by methionine adenosyltransferase 2A (MAT2A), which is deregulated in different cancer types." (PMID 32456310, 2020). "Taken together, MAT2A and MAT2B are important targets of miR-34a/b and SAMe and MTA target this axis, suppressing MAT2A/MAT2B while raising miR-34a/b expression, inhibiting cancer metastasis." (PMID 29108270, 2017). "MAT2A and MAT2B proteins are induced in multiple cancers in parallel because they stabilize each other." (PMID 29108270, 2017). "In summary, we have identified MAT2A and MAT2B as direct and indirect targets of miR-34a and miR-34b, and that the two MAT proteins are important mediators of the effect of miR-34a/b on cancer cell growth, migration and invasion." (PMID 29108270, 2017). "Here we confirmed that the two MAT proteins stabilize each other using knockdown of endogenous MAT2A and MAT2B in multiple human cancer cell lines." (PMID 29108270, 2017). "Application of the integrative modelling to cancer genes revealed a major role for MAT enzymes (MAT2B and MAT2A), as well as PHGDH and GATM—enzymes involved in serine and glycine metabolism, respectively." (PMID 27966532, 2016). "Including transcripts from MAT2A and MDM2, 27.8% of significant DE transcripts in PBAFB were annotated to genes with known roles in cancer or apoptosis." (PMID 24979717, 2014). "The MAT1A:MAT2A switch, which was accompanied with an increasing expression of MAT2B, results in decreasing SAM levels and facilitates cancer cell growth." (PMID 24098708, 2013). "The increased expression of MAT2A and MAT2B in HCC results in decreasing SAM levels and facilitates cancer cell growth." (PMID 24098708, 2013). "Elevated MAT2A expression occurs in multiple cancers and has been considered as a negative prognostic indicator, including in CRC." (PMID 41331630, 2025). "This MTAP deletion-induced vulnerability is extend to the MAT2A, the upstream enzymes of PRMT5, and three kinds of MAT2A inhibitor (AG-270, S-095033, and IDE-397) are currently in the phase I clinical trials for the therapy of MTAP-deleted cancers." (PMID 41445748, 2025). "Recent studies have identified that the absence of MTAP in cancer cells renders them more susceptible to PRMT5 and MAT2A depletion." (PMID 40430461, 2025). "Interestingly, SAMe and MTA promote miR-34a/b expression reducing MAT2A and MAT2B abundance and inhibiting cancer metastasis." (PMID 39941901, 2025). "The combination of MTAP and MAT2a inhibitors expands this synthetic lethal approach to include MTAP+/+ cancers, especially the remaining 98% of CRCs without the MTAP−/− genotype." (PMID 38000655, 2024). "Discovering the synthetic lethal interaction between MAT2A and MTAP, it was proposed that MAT2A inhibitors could be a promising strategy to suppress the proliferation of MTAP‐deleted cancers." (PMID 39309689, 2024).
cancer (continued). "Therapies targeting of MAT2A, RIOK1, or other PRMT5 co‐complex members selectively affect MTAP‐deleted cancers while sparing MTAP‐expressing normal tissues, which address the unmet clinical need of human cancers with the deletion of the MTAP locus." (PMID 39711357, 2024). "Recently, targeting PRMT5, or MAT2A that impacts PRMT5 activity by producing SAM, has shown promise as a therapeutic strategy in oncology, generating synthetic lethality in MTAP-negative cancers." (PMID 37795443, 2023). "Methionine adenosyltransferase II alpha (MAT2A) is expressed in most tissues and cancer cells and is a key enzyme that utilizes methionine to produce S-adenosyl methionine (SAM) in both normal and cancer cells." (PMID 36572880, 2022). "Additionally, the functional assay demonstrated that double knockdown MAT2A and/or VCIP135 significantly represses cancer cell growth." (PMID 35729157, 2022). "The dysregulation of c-Myc in cancer cells promoted TRIM32 expression, which ubiquitinated SIRT4 for the proteasome-dependent degradation, thereby facilitating methionine cycle by reducing the ADP-ribosylation modification of MAT2A." (PMID 36371321, 2022). "Thus, the team at Agios Pharmaceuticals in the US demonstrated the mechanism by which MAT2A inhibition induces DNA damage and mitotic defects in MTAP-deleted cancers using RNA sequencing and proteomics." (PMID 34063807, 2021). "MTDIA causes a physiologic inactivation of MTAP and may also have efficacy in combination with inhibitors of MAT2A or PRMT5, known synthetic-lethal interactions in MTAP−/− cancer cell lines." (PMID 33893330, 2021). "Elevated MTA concentrations in MTAP−/− cancer cells provide partial inhibition of PRMT5, which would be enhanced in terms of cancer cell lethality when combined with an inhibitor of PRMT5 directly or with an inhibitor of MAT2A, which supplies SAM for PRMT5." (PMID 33893330, 2021). "The recent observation that the inhibition of MAT2A and MAT2B expression by miRNAs leads to a rise of endogenous SAM and strong inhibition of cancer cell growth could open new perspectives to the treatment of HCC." (PMID 31234428, 2019). "Three recent studies have reported an increased dependency of cancer cells harboring a homozygous deletion of the MTAP gene on PRMT5, WDR77 and RIOK1, all members of a PRMT5 containing complex, and the upstream component MAT2A." (PMID 29983885, 2018). "The aims of the current work were to examine whether miR-34 family members regulate MAT2A and MAT2B expression and whether SAMe and MTA target this axis in multiple human cancers where miR-34a has been reported to be down-regulated." (PMID 29108270, 2017). "Previous studies have shown that the ratio of the expression of MAT1A, an oncogene, to that of MAT2A is positively correlated with HCC survival, the conversion of MAT1A to MAT2A reduces the biosynthesis of S-adenosylmethionine (SAMe), providing favorable conditions for cancer cell growth." (PMID 41513616, 2026). "Therefore, limiting methionine intake or targeting MAT2A may be a promising strategy for treating GBM and other cancer types." (PMID 39872059, 2023). "Thus, the complicated role of SAM may be involved in the metabolic vulnerabilities of MAT2A enzyme or SAM levels in HCC and other cancers." (PMID 37166978, 2023). "The MAT2A node includes TIGD6, which has not been associated with cancer." (PMID 34797887, 2021). "Induction of MAT2A/MAT2B confers growth and survival advantage to cancerous cells and enhancing tumor migration; hence, understanding the role of MAT genes in tumorigenesis can help develop potential and effective strategies for cancer treatment and chemoprevention." (PMID 34065390, 2021). "MAT2A is not known to enhance cancer cell migration or invasion." (PMID 29108270, 2017). "Thus, MAT2A inhibition by a small molecule may be difficult to target, unless an optimal dosage is found that impairs cancer growth and lowers the SAM levels enough without triggering an epigenetic response." (PMID 32824193, 2020).